FAM221B (family with sequence similarity 221 member B)
Synonyms: C9orf128
Tractability: No criterion of Open Targets' tractability assessment is met for any kind of drug.
Gene: Protein-coding gene on chromosome 9 (35,816,391 to 35,828,747, reverse strand). Ensembl gene ENSG00000204930.
Gene Ontology:
Molecular function: protein binding
Genetic constraint (gnomAD): Loss-of-function variants: 33 observed, 40.19 expected, observed/expected ratio (o/e) 0.82, 90% interval 0.62 to 1.1. The upper end of that interval is the gene's LOEUF score, 1.1, which puts it in group 4 of 6, group 1 being the genes least tolerant of losing a copy. Missense variants: 472 observed, 521.3 expected, observed/expected ratio (o/e) 0.91, 90% interval 0.84 to 0.98. Synonymous variants: 157 observed, 185.53 expected, observed/expected ratio (o/e) 0.85, 90% interval 0.74 to 0.97.
Homologues: Orthologues: chimpanzee FAM221B (99% identical), macaque FAM221B (92% identical), dog FAM221B (66% identical), pig FAM221B (64% identical), guinea pig FAM221B (60% identical), mouse Fam221b (56% identical), rat Fam221b (56% identical). Paralogues in human: FAM221A (14% identical).